AR (androgen receptor)
Diseases named in the same sentence as AR in open-access papers (continued):
Sharing a sentence is not in itself a finding about the gene and the disease.
prostate carcinoma (continued). "ACSL3 is an androgen receptor (AR)-stimulated gene and was recently identified in formalin-fixed prostate cancer tissue as a new 5′ translocation partner of ETS variant 1 (ETV1), an important gene in driving prostate cancer progression." (PMID 29156692, 2017). "In summary, our meta-analysis indicated that short CAG and GGN repeats in androgen receptor gene were associated with increased risk of prostate cancer, especially in Caucasians." (PMID 28091563, 2017). "Considering the requirement of AR to promote prostate cancer and the association of RNase L with genetic predisposition to HPC, we explored the mechanisms that underlie tumor suppression." (PMID 28257035, 2017). "We also studied the expression of AURKA in clinical prostate cancer samples and its association with the AR expression levels." (PMID 29269934, 2017). "Our results show that Cao2+ induces filamin A cleavage and promotes migration in AR-deficient and highly metastatic prostate cancer cells via a CaR-p115RhoGEF-calpain signaling pathway." (PMID 27206800, 2017). "Supporting ARv7 protein or RNA expression being a potentially useful biomarker for disease progression, AR variant splice isoform levels change during prostate cancer development." (PMID 28382513, 2017). "In the present study, we further demonstrate that GPCR signaling, independent of AR, can activate the cleavage of filamin A to promote cell migration in AR- deficient and highly metastatic prostate cancer cells." (PMID 27206800, 2017). "Prostate cancer (PCa) is the second leading cause of cancer mortality in American men and is dependent on the activity of androgen receptor (AR) for its initiation and progression." (PMID 28036278, 2017). "The AR is causally linked to prostate cancer and androgen-AR signaling is critical for prostate cancer development and progression." (PMID 28212551, 2017). "CaR-Gα12-p115RhoGEF signaling stimulates choline kinase activity in AR-deficient and highly metastatic prostate cancer cells." (PMID 27206800, 2017). "The protein expression in androgen receptor positive prostate cancer cells is associated with prostate cancer outcome and relapse." (PMID 29299148, 2017). "Meanwhile, filamin A is also found to be overexpressed in breast cancer and AR-deficient prostate cancer cells." (PMID 27206800, 2017). "Anti-androgens hydroxyflutamide and bicalutamide have been used over many years in prostate cancer treatment, and the studies on resistance mechanisms were particularly focused on AR mutations which emerge during endocrine therapy with these compounds." (PMID 29214142, 2017). "Herein we outline the role of the PI3K pathway in prostate cancer and, in particular, its association with androgen receptor signaling in the pathogenesis and evolution of prostate cancer, as well as a review of the clinical utility of PI3K targeting." (PMID 28420128, 2017). "The present meta-analysis summarizes the evidence to date regarding the association between CAG and GGN repeat polymorphisms of androgen receptor and the risk of prostate cancer." (PMID 28091563, 2017). "Increased expression of variant transcripts from the AR gene (ARVs) has been shown to be involved in the development of castration-resistant prostate cancer." (PMID 28475115, 2017). "Taken together, our results show that differential expression of miR-34b and AR are associated with prostate cancer aggressiveness in African-Americans." (PMID 28039468, 2017). "We show here that loss of both Apc and Smad4 results in invasive, castration-resistant prostate carcinoma with androgen receptor (AR) loss." (PMID 29113300, 2017).
prostate carcinoma (continued). "AR is expressed in almost all primary prostate cancers and most castration-resistant prostate cancers, however, AR expression loss in prostate tumor cells has been reported." (PMID 28765837, 2017). "Still, the mechanisms implicated in the development of resistance to AR inhibition in prostate cancer are multiple and complex, involving virtually all classes of genomic alteration and leading to a host of selective/adaptive responses." (PMID 28380417, 2017). "The meta-analysis showed that short CAG and GGN repeats in androgen receptor gene were associated with increased risk of prostate cancer, especially in Caucasians." (PMID 28091563, 2017). "In prostate cancer, interleukin-4 has been associated with activation of the androgen receptor, increased proliferation and activation of survival pathways such as Akt and NF-κB." (PMID 28553931, 2017). "In the current study, we demonstrate that low miR-34b expression is responsible for aberrant expression of AR associated with prostate cancer progression and aggressiveness, especially among African-American men." (PMID 28039468, 2017). "The proportions of AR mutations in prostate cancer are 40% in the NTD, 49% in the LBD, and 7% in the DBD." (PMID 28264478, 2017). "Prostate cancer is the most common cancer in men, and increased AR activity is associated with prostate cancer development and progression." (PMID 28415728, 2017). "In hormone-dependent cancers (e.g., breast and prostate cancer), steroid hormones trigger association of the androgen receptor (AR)-estradiol receptor (ER) complex with Src." (PMID 28606127, 2017). "For example, sentences similar to “The standard systemic treatment for prostate cancer (PCa) is androgen ablation, which causes tumor regression by inhibiting activity of the androgen receptor (AR)." (PMID 29029598, 2017). "For its treatment, hormonal strategies [e.g., androgen ablation therapy and/or androgen receptor (AR) antagonists] are used to prevent AR signalling associated with the development and progression of prostate cancer." (PMID 28599655, 2017). "The results suggested that short CAG and GGN repeats in the androgen receptor gene were associated with increased risk of prostate cancer, especially in Caucasians." (PMID 28091563, 2017). "It is clear that CaR-mediated signaling pathways play an important and specific role in the regulation of AR-deficient and highly metastatic prostate cancer cell migration." (PMID 27206800, 2017). "We therefore asked if H2A.Zac nucleosomes that flank AR-enhancers are associated with any of the AR co-factors with a known oncogenic role in prostate cancer, including CtBP131, CtBP232, FOXA-1, and GATA-233." (PMID 29116202, 2017). "To discover germline events involved in prostate cancer predisposition, we develop a computational approach to nominate heritable facilitators of somatic genomic events in the context of the androgen receptor signaling." (PMID 28663546, 2017). "Two landmark papers defined the interplay between PTEN loss/PI3K activation and AR signaling in the development of prostate cancer." (PMID 28420128, 2017). "Higher prostate epithelium AR levels increase the progression to castration-resistant prostate cancer in men, proliferative rate, and prostate cancer risk in rat probasin-murine AR (Pb-mAR) transgenic mice." (PMID 28765837, 2017). "We also showed that CREB3L4 directly associates with AR, to enhance AR-induced transactivation of its downstream genes, in prostate cancer cells." (PMID 28338058, 2017).
prostate carcinoma (continued). "We have previously shown that down regulation of PrKD1 is associated with prostate cancer progression through several molecular mechanisms including nuclear translocation of beta-catenin and by influencing AR transcriptional activity." (PMID 29108267, 2017). "Dimerized SGTA is an inhibitor of dynein motor-dependent AR transport and signalling, which is the cause of the androgen-independent condition in human prostate cancer." (PMID 28599655, 2017). "For example, AR mutations or gene amplifications can confer resistance to antiandrogen therapy in prostate cancer, including Enz, and estrogen receptor (ER) mutations confer resistance to ER pathway therapies in breast cancer." (PMID 28891793, 2017). "Overall, all currently published patient-based studies indicate that lower AR in prostate cancer stroma is associated with disease progression and/or worse outcome, implying that stromal AR is protective." (PMID 28117763, 2017). "We also observed inverse correlation of miR-34b and AR expression in our African-American tissue samples, suggesting that our clinical data demonstrate that miR-34b and AR are associated with aggressiveness of African-American prostate cancer." (PMID 28039468, 2017). "For example, in addition to the involvement of GR in prostate cancer, GR and AR have been implicated in a subtype-specific breast cancer progression." (PMID 28191869, 2017). "AR isoform encoded by splice variant 7 lacks the ligand-binding domain and is associated with the resistance to hormonal prostate cancer therapies, especially enzalutamide and abiraterone." (PMID 29228644, 2017). "Although hormone-ablation therapy is efficient for androgen receptor AR-dependent prostate cancer prevention, the AR-independent pathway also causes prostate cancer." (PMID 29215592, 2017). "Further evidence has been obtained to show that both AR and non-AR pathways have been implicated in acquisition of therapy resistance in prostate cancer in models that exhibited increased metastatic growth." (PMID 29214142, 2017). "Fortunately, neuroendocrine prostate cancers and refractory therapy-resistant AR mutations are rare among prostate cancer patients." (PMID 28380417, 2017). "HPC1-associated mutations in RNase L enhance AR signaling and cell migration and our study has identified a novel role of RNase L as a prostate cancer susceptibility gene." (PMID 28257035, 2017). "It is hoped that understanding the splicing pathways generating AR splice variants will lead to downstream clinical applications used to treat prostate cancer." (PMID 28382513, 2017). "The results indicate that calpains, most likely calpain 1, play a critical role in Cao2+-induced filamin A cleavage, which leads to a remodeling of actin cytoskeleton and an increase in the migration of AR-deficient prostate cancer cells." (PMID 27206800, 2017). "Many of these AR-target DNA repair genes with increased expression in prostate cancer also had higher expression levels in the high-risk IPLs in this study." (PMID 28978094, 2017). "Further analyses need to be performed to validate this model and to understand how AR variants induce a decrease of endogenous AR-FL in prostate cancer cells." (PMID 29069764, 2017). "Aberrant restoration of AR activity is linked with prostate tumor growth, therapeutic failures and development of castrate-resistant prostate cancer." (PMID 28852180, 2017). "Constitutively active androgen receptor (AR) variants have been involved in the expression of mesenchymal markers such as N-cadherin in prostate cancer (PCa)." (PMID 29069764, 2017). "Although we documented Cao2+- induced filamin A cleavage, and identified part of the CaR- mediated signaling pathway in AR-deficient and highly metastatic prostate cancer cells." (PMID 27206800, 2017).
prostate carcinoma (continued). "The most prevalent HPC1-associated mutations in RNase L, R462Q and E265X, enhanced AR signaling and cell migration and our studies identify a novel role of RNase L as a prostate cancer susceptibility gene." (PMID 28257035, 2017). "Our results provide a potential rationale for a therapeutic strategy in treatment of AR-deficient prostate cancer and a mechanism of CRPC development." (PMID 27206800, 2017). "We stably transfected LNCaP cells (androgen sensitive prostate cancer cell line with high expression of PrKD1 and AR), with T120-mutated beta-catenin, wild type beta-catenin (WT) or empty vector." (PMID 29108267, 2017). "Although the association between CAG and GGN repeats in the androgen receptor gene and prostate cancer risk has been widely studied, it remains controversial from previous meta-analyses and narrative reviews." (PMID 28091563, 2017). "Taken together, our results demonstrate that Cao2+ activates CaR-mediated signaling and induces the cleavage of filamin A via calpain activation, and this cleavage promotes the migration of AR-deficient and highly metastatic prostate cancer cells." (PMID 27206800, 2017). "Our data show that Cao2+ via CaR-mediated signaling induces filamin A cleavage and promotes the migration in AR-deficient and highly metastatic prostate cancer cells." (PMID 27206800, 2017). "Deletion and mutations in ASXL2, a chromatin/histone modifier gene that interacts with AR, are associated with castration resistant prostate cancer." (PMID 28945760, 2017). "Androgen receptor (AR) signaling has been reported to have a critical role associated with prostate cancer in racial disparities." (PMID 28039468, 2017). "Our further studies demonstrate that the cleavage of filamin A is regulated by CaR-mediated signaling and promotes the migration of AR-deficient prostate cancer cell lines." (PMID 27206800, 2017). "Overall, our results enrolled 51 studies indicated that significant increased risk of prostate cancer was associated with androgen receptor CAG polymorphism (OR = 0.77, 95% CI: 0.67–0.89)." (PMID 28640128, 2017). "The human prostate cancer cell line VCaP (vertebral cancer of the prostate) overexpresses AR and its splice variants (ARVs) as a mechanism of resistance to androgen-deprivation therapy (ADT) of external and intratumoral origin." (PMID 28380417, 2017). "Nevertheless, for patients with advanced disease with castration resistant prostate cancer characterised by a constitutive activation of AR, depending on AR gene point mutations or truncations, there is an urgent need to develop new treatments." (PMID 28415632, 2017). "The association between choline uptake and androgen receptor (AR) expression is suggested by the upregulation of choline kinase-alpha in prostate cancer." (PMID 29138500, 2017). "This interaction can also be of clinical relevance in prostate cancer, as AR splice variants that lack an intact DNA-binding domain are described as one of the mechanisms promoting CRPC." (PMID 28511652, 2017). "Using the prostate cancer LNCaP cell line, which is also endowed with AR-T877A mutated variant, we observe that 50 and 100 μM BPA causes cell cycle arrest which is mediated by a non-transcriptional mechanism involving EGFR, ERK, AR, and ERβ." (PMID 29383186, 2017). "These therapies have proven effective in the initial treatment of prostate cancer as PC cells are unable to tolerate an acute loss of circulating testosterone or interrupted AR signaling and undergo apoptosis as a result." (PMID 28212321, 2017). "The androgen receptor gene (AR – located on the X chromosome) has been studied by means of the genetic variants both in relation with the risk of developing prostate cancer and the progression of the disease." (PMID 28255369, 2017). "These indicate that our clinical data demonstrate that miR-34b correlates with AR expression and are associated with aggressiveness of prostate cancer in African-American males." (PMID 28039468, 2017).
prostate carcinoma (continued). "Deregulation of the AR signaling pathway, most likely through AR, is associated with the formation and development of primary prostate cancer as well as castration resistant prostate cancer (CRPC) progression." (PMID 27835608, 2016). "In support of this possibility, PCGEM1 is correlated with AR3, a predominant and clinically important form of AR splice variants in prostate cancer." (PMID 26848868, 2016). "In PRAD, cooperation of SREBF and AR signaling has been linked to progression of prostate cancer cells." (PMID 27623747, 2016). "FoxA1 determines AR genomic binding in cultured prostate cancer cells and is frequently mutated in human prostate cancer." (PMID 27374105, 2016). "In the current study, we investigated very specific patients with double primary cancers of the bladder and prostate who received ADT for their prostate cancer and showed that AR positivity in BCs correlated with a reduced risk of tumor recurrence." (PMID 26885620, 2016). "Although it is still unclear how prostate cancer growth changes from being hormone dependent to hormone independent, AR activation via amplification and mutation and/or related AR signaling is considered to play a key role." (PMID 27493956, 2016). "FOXA1 mutationstend to occur in the DNA-binding domain, and preliminary data from prostate cancer suggest that mutations inFOXA1 decrease AR signalling and increase tumour growth." (PMID 26884552, 2016). "Consistent with a role for DNAH8 in promoting AR activity and prostate cancer progression, DNAH8 resided in a cancer-associated amplicon, and contained a coding SNP in prostate cancer." (PMID 27363033, 2016). "The stimulation of AR signalling leads to activation of SRC oncogenic kinases that phosphorylate AR in prostate cancer cells and cause castration resistance and cellular proliferation and invasiveness." (PMID 26682011, 2016). "With regard to prostate cancer biology, particularly underlined are multidimensional relations between NF-κB pathway activation and activation of signaling pathways dependent on androgen receptor." (PMID 27975057, 2016). "Increased sensitivity of AR has been related to increased testosterone effect (androgen activity) and associated with androgen-dependent conditions, e.g. prostate cancer or benign prostate hyperplasia." (PMID 26910733, 2016). "Aberrant AR-dependent transcriptional programs also underlie the development of late stage (i.e. metastatic) castration-resistant prostate cancers." (PMID 27365400, 2016). "Although AR plays a key role in carcinogenesis of prostate cancer, the results in this study showed that the AR index is only of borderline significance in its association with reduced patient survival time (log-rank test, p = 0.052)." (PMID 27779102, 2016). "The β2-adrenergic receptor (ADRB2) and its downstream effectors cyclic AMP (cAMP) and cAMP-dependent protein kinase A (PKA) have been implicated in prostate cancer progression and AR signaling." (PMID 26646591, 2016). "AR signalling is frequently implicated as a driver of tumour growth in prostate cancer, and anti-androgen therapy has long been a mainstay of the treatment of advanced disease." (PMID 26894753, 2016). "Activation of the PI3-kinase (PI3K) axis from PTEN deficiency suppressed AR transcriptional output in murine models of prostate cancer." (PMID 27557496, 2016). "Several AR mutations in this binding site have been associated with poor prognosis and resistance to conventional prostate cancer drugs." (PMID 26813233, 2016). "The incidence of AR mutations is rare in untreated prostate cancer, and is estimated to be in the range of 15 % in CRPC patients." (PMID 26813233, 2016). "Cyproterone acetate, hydroxyflutamide and nilutamide stimulate AR T877A, the first AR mutation identified in prostate cancer." (PMID 26760770, 2016). "The role of AR splice variants in CRPC has been functionally characterized in recent years due to their prevalence in advanced prostate cancer tissues." (PMID 27049719, 2016).